SMIM38 (small integral membrane protein 38)
Gene: Protein-coding gene on chromosome 11 (69,155,478 to 69,162,440, forward strand). Ensembl gene ENSG00000284713.
Subcellular location: Membrane
Gene Ontology:
Cellular component: membrane
Homologues: Orthologues: chimpanzee SMIM38 (100% identical), rat Smim38 (69% identical), mouse Smim38 (67% identical).